RALGDS (ral guanine nucleotide dissociation stimulator)
Description:
Functions as a guanine nucleotide exchange factor (GEF) activating either RalA or RalB GTPases and plays an important role in intracellular transport. Interacts and acts as an effector molecule for R-Ras, H-Ras, K-Ras, and Rap (By similarity). During bacterial clearance, recognizes 'Lys-33'-linked polyubiquitinated TRAF3 and subsequently mediates assembly of the exocyst complex.
Synonyms: RalGEF; RGF; RGDS
Tractability: Antibody: its Gene Ontology location is reachable by antibodies, with medium confidence.
Gene: Protein-coding gene on chromosome 9 (133,097,719 to 133,149,334, reverse strand). Ensembl gene ENSG00000160271.
Subcellular location: Cytoplasm; Nucleus
Subcellular location (Human Protein Atlas): Nucleoplasm
Pathways (Reactome):
Signal Transduction: RAF/MAP kinase cascade; p38MAPK events
Gene Ontology:
Molecular function: GTPase regulator activity; protein binding; guanyl-nucleotide exchange factor activity
Biological process: Ras protein signal transduction; signal transduction; small GTPase-mediated signal transduction
Cellular component: brush border; cytosol; nucleus; cytoplasm; plasma membrane
Genetic constraint (gnomAD): Loss-of-function variants: 43 observed, 94.19 expected, observed/expected ratio (o/e) 0.46, 90% interval 0.36 to 0.59. The upper end of that interval is the gene's LOEUF score, 0.59, which puts it in group 2 of 6, group 1 being the genes least tolerant of losing a copy. Missense variants: 1,022 observed, 1,171.7 expected, observed/expected ratio (o/e) 0.87, 90% interval 0.83 to 0.92. Synonymous variants: 529 observed, 489.43 expected, observed/expected ratio (o/e) 1.08, 90% interval 1.01 to 1.16.
Homologues: Orthologues: chimpanzee RALGDS (99% identical), macaque RALGDS (91% identical), dog RALGDS (90% identical), guinea pig RALGDS (87% identical), pig RALGDS (87% identical), mouse Ralgds (87% identical), rat Ralgds (85% identical), tropical clawed frog ralgds (64% identical), zebrafish ralgds (54% identical), tropical clawed frog zbtb22 (27% identical). Paralogues in human: RGL1 (41% identical), RGL3 (32% identical), RGL2 (29% identical), RGL4 (20% identical), RAPGEF2 (18% identical), RAPGEF6 (17% identical), RAPGEF1 (15% identical), SOS2 (14% identical), RASGRF2 (14% identical), RASGRF1 (14% identical), SOS1 (13% identical), RASGRP1 (13% identical), and 12 more.
Diseases named in the same sentence as RALGDS in open-access papers:
RALGDS is named in the same sentence as 28 diseases in open-access papers, as found by Europe PMC text mining. Sharing a sentence is not in itself a finding about the gene and the disease. The quoted sentences say what the papers report.
breast carcinoma (4 papers, 2014 to 2025). "Numerous studies have established associations between RalGDS isoforms and the pathogenesis of various diseases, including skin cancer, breast cancer, and cardiovascular diseases." (PMID 40729035, 2025). "Our data suggest that RILP suppresses the invasion of breast cancer cells by interacting with RalGDS to inhibit its GEF activity for RalA." (PMID 26469971, 2015). "Our results suggest that RILP suppresses the invasion of breast cancer cells by modulating the activity of RalA through interaction with RalGDS." (PMID 26469971, 2015). "Taken together, RILP may inhibit the invasion of breast cancer cells by modulating the activity of RalA through the interaction with RalGDS to negatively regulate the GEF function." (PMID 26469971, 2015). "Following treatment with NAC and prior to surgery, serum samples obtained from 120 patients with stage II/III breast cancer were subjected to the OS-MSP assay for analysis of the glutathione S-transferase pi 1, Ras association (RalGDS/AF-6) domain family member 1 and retinoic acid receptor β2 genes." (PMID 24959284, 2014). "As RalGDS functions as Ras-dependent GEF for Ral small GTPases, and is an important regulator in cancer behavior, the interaction of RILP with RalGDS is probably the mechanism (or part of the mechanism) for RILP regulating the proliferation, migration and invasion of breast cancer cells." (PMID 26469971, 2015).
pancreatic cancer (3 papers, 2020 to 2025). "In the pancreatic cancer pathway, for example, mutation-activated KRAS signaling through RalGDS involves PA via phospholipase D1/2 (PLD1/2)." (PMID 39676871, 2024). "ALDOA and PAF1 have recently been described as oncogenes in PDAC, whereas ENO1, RALGDS, TRIP10, and FLNA are known to mediate pancreatic cancer cell proliferation, survival and migration." (PMID 32029502, 2020).
cardiac hypertrophy (2 papers, 2013 to 2025). "There have been advances in RALB in cardiovascular disease; for example, RALB is required for autophagy in mTOR-dependent cardiomyocytes, and RALB-associated RalGDS-mediated autophagy induction and exocyst function is critical for load-induced cardiac hypertrophy." (PMID 41398523, 2025).
bladder cancer (1 paper, 2017). "It is known in bladder cancer cells that the loss of E-cadherin interaction with RalGDS (an activator of RalA) results in robust endocytosis during blebbishield formation." (PMID 28851898, 2017).
breast tumors (1 paper, 2013). "Since the Ral guanine exchange factor, RalGDS, strongly associates with β-arrestins and Rap1A GTPases, we determined if the expression of Rap1A was also altered in patient breast tumors." (PMID 23405264, 2013).
COVID-19 (1 paper, 2023). A disease caused by infection with severe acute respiratory syndrome coronavirus 2. "Colocalization of 2/4 single-cell eQTLs was specific to cell type with 3/3 from stimulated cells specific to cell state with colocalization for RALGDS, for example, specific to T effector memory cells 16 h post-stimulation for severe and susceptibility to COVID-19." (PMID 37640912, 2023). "While RALGDS was mapped, its contributory cis-eQTLs were mapped around ABO, which has been suggested to mediate COVID-19 pathogenesis via glycosylation of downstream targets and colocalized in others’ studies, underscoring the complexity of mapping eQTLs." (PMID 37640912, 2023).
diabetes mellitus (1 paper, 2020). A metabolic disorder characterized by abnormally high blood sugar levels due to diminished production of insulin or insulin resistance/desensitization. "In addition, RalGDS activates Akt kinase whose abnormal expression is implicated in diabetes mellitus pathology." (PMID 32075680, 2020).
head and neck cancer (1 paper, 2017). A primary or metastatic malignant neoplasm affecting the head and neck. "Alternatively, this pattern might suggest that a shift in HRAS binding preference from FHOD1 to another partner such as RALGDS is favorable for head and neck cancer but less favorable for thyroid cancer." (PMID 28815022, 2017).
lupus (1 paper, 2016). "RALGDS was reported in SLE PBMCs whereas MT2A and GRB2 were observed to be upregulated in lupus T cells." (PMID 27835693, 2016).
pancreatic adenocarcinoma (1 paper, 2021). "Conversely, the expression levels of CCND1, DUSP2, ETS2, JUN, and RALGDS were decreased in lung and pancreatic adenocarcinomas with KRAS mutations." (PMID 33982211, 2021).
steatosis (1 paper, 2021). Increased lipid within the cytoplasm of cells. "NAMPT, PHLDA1, RALGDS, GADD45B, and FOSL2 were all in the brown module, with a lower expression for steatosis and NASH samples and with a higher expression for normal samples." (PMID 34041361, 2021).
cancer (17 papers, 2013 to 2025). A tumor composed of atypical neoplastic, often pleomorphic cells that invade other tissues. "RALGDS encodes a guanylyl-nucleotide exchange factor (GEFs) specifically involved in signal transduction pathways regulating cell growth and cancer/tumorigenesis in humans." (PMID 32075680, 2020). "Pathway analysis highlighted the involvement of the MAPK and RAS signaling pathways in cancer development and proteomics analysis identified RALGDS as a key protein." (PMID 40157967, 2025). "We also identified 5 genes (LGR4, RARG, PNISR, PCOLCE2, RALGDS) that shared the same patterns across three types of cancer, and 39 genes with two overlaps across eight cancer types." (PMID 32764426, 2020). "These include KRAS, HRAS and NRAS and a variety of different mutations that mirror those found in human cancers with the major RAS effectors such as CRAF, PI3K and RALGDS." (PMID 29989546, 2018). "Notably, these recurrent SLRs were associated with genes known to be implicated in cancer, as evidenced by the Catalogue of Somatic Mutations in Cancer (COSMIC), including RALGDS, BCR, SH2B3, LMNA, and GATA2." (PMID 40193528, 2025). "Recent studies highlight RALGDS’s essential role in modulating KRAS-driven oncogenic pathways, linking RALGDS activity to enhanced tumor growth and metastasis in various cancers." (PMID 40157967, 2025). "First, some upstream components, such as EGFR, other RTKs, and Ras, activate multiple downstream effectors, in addition to the Raf-MEK-Erk arm, including cancer promoting components (e.g., the PI3K-AKT/PKB pathway, RalGDS, PKCε, PKCζ, Src;." (PMID 40394416, 2025). "Ki-RAS has four effectors that all play a role in cancer development: the MAPK pathway, the PI3K pathway, Ral guanine nucleotide dissociation stimulator (Ral-GDS), and RAC1." (PMID 28499439, 2017). "Ras can activate three major pathways, the Raf, RalGDS, and PI3K pathways, all of which contribute to the fully transformed phenotype of cancer cells." (PMID 26301220, 2015). "The third effector pathway downstream of Ras, the RalGDS-Ral pathway, has not yet been successfully targeted therapeutically despite growing evidence implicating this pathway as a critical mediator of survival in several Ras-mutant cancers, including pancreatic, colorectal, bladder, and melanoma." (PMID 33214225, 2021). "Together, we hypothesize that RILP interacts with RalGDS, and consequently inhibits its GEF activity, resulting in inhibition of RalA activation, thus suppresses the secretion and cytoskeleton reconstruction required for cell migration and invasion of cancer cells." (PMID 26469971, 2015).
tumor (16 papers, 2009 to 2025). "Some of these switches occur in known tumor drivers, including PPARG, CCND3, RALGDS, MITF, PRDM1, ABI1 and MYH11, for which the switch implies a change in the protein product." (PMID 25578962, 2015).
Bacterial infections (1 paper, 2021). "Pathway analysis revealed multiple related functions of the new features, such as Viral mRNA Translation (INMT), GABA receptor binding (GABARAP), Bacterial infections in CF airways (TOLLIP), signaling (RALGDS) and others." (PMID 34302024, 2021).
RALGDS also shares sentences with these, for which no sentence is quoted: colorectal cancer (3 papers); cardiovascular disease (2); fibrosarcoma (2); Obesity (2); prostate carcinoma (2); skin cancer (2); -dependent (1); leukemia (1); lung carcinoma (1); melanoma (1); non-small cell lung carcinoma (1); renal cell carcinoma (1); reovirus infection (1); thyroid cancer (1).